H19 (H19 imprinted maternally expressed transcript)
Diseases named in the same sentence as H19 in open-access papers (continued):
Sharing a sentence is not in itself a finding about the gene and the disease.
cancer (continued). "Various lncRNAs, such as ROR, HOTAIR, H19, UCA1, and ARSR, are involved in cancer stemness." (PMID 29299179, 2017). "With a fixed-effect model, non-female cancer patients with high H19 expression had a shorter DFS than those with low H19 expression (pooling HR = 1.43, 95 % CI = 1.23 - 1.66, p < 0.0001)." (PMID 27926484, 2017). "We propose here that H19, in conjunction with SAHH, may contribute to alterations in the epigenetic landscape in cancer cells." (PMID 27775072, 2017). "The most frequently epimutated regions varied depending on tissue origin, with the maternally methylated ZNF597 DMR being affected in 66.6% of hepatocarcinoma cell lines, H19 in 28.9 % of lung, ZNF331 DMR1 in 32% of colon and GRB10 in 44.9% of breast-derived cancer cell lines." (PMID 28883545, 2017). "Kallen noted that H19 harbors both canonical and non-canonical binding sites for the let-7 family of micro-RNAs, which plays important roles in development, cancer, and metabolism." (PMID 28738810, 2017). "Under a random-effect model, non-female cancer patients with high H19 expression had shorter OS than those with low H19 expression (pooling HR = 1.33, 95 % CI = 1.11 - 1.59, p = 0.002)." (PMID 27926484, 2017). "H19 is involved in EMT and promotes cancer cell proliferation, invasion, and metastasis." (PMID 29088808, 2017). "We found that HOTAIR, H19 and TUG1 almost appeared in all cancer types." (PMID 28076842, 2017). "A shorter OS (pooling HR = 1.19, 95% CI = 1.08 - 1.31, p = 0.0004) was observed in non-female cancer patients with higher H19 expression compared with those with lower H19 expression under a fixed-effect model." (PMID 27926484, 2017). "In the meta-analysis, patients with high H19 expression showed a poorer outcome in non-female cancer (p<0.05)." (PMID 27926484, 2017). "With a random-effect model, shorter OS was observed in non-female cancer patients with high H19 expression than those with low H19 expression (pooling HR = 1.31, 95 % CI = 1.09 - 1.59, p = 0.004)." (PMID 27926484, 2017). "Except that H19 could promote ESCC cell proliferation and metastasis, PVT1 as a rising star among oncogenic lncRNAs has been reported in plenty of cancers." (PMID 27966444, 2016). "H19 expression was up-regulated in the PC cancer tissue compared with that in the adjacent non-cancer tissue." (PMID 27429196, 2016). "Finally, not only did this study reveal the function of H19 in GBM cells, it also added evidence supporting the role of lncRNA in cancer." (PMID 26983719, 2016). "Other lncRNAs (e.g., EBIC, H19, PVT1, and MALAT1) also interact with EZH2 in cancer cells, and may promote malignancy in GC by altering EZH2 activity." (PMID 26799422, 2016). "In this context, although it appears that H19 consistently promotes the development of multiple types of cancers, its mechanism of action is not understood." (PMID 26872375, 2016). "Our results indicate a previously unknown link between H19, oxidative reduction, and GSH metabolism in the regulation of cancer-drug resistance." (PMID 27193186, 2016). "In the present study, we identified lncRNA H19 as a novel player in modulating EMT progress and revealed a previously unknown mechanism involving H19 and EMT-related miRNAs in cancer biology." (PMID 26068968, 2015). "However, only 19 long noncoding RNAs from the LncRNADisease were found among the ESCALs, these including several lncRNAs such as HOTAIR, PVT1, H19 and GAS5 that have been reported to be dysregulated in multiple human cancers." (PMID 26158411, 2015). "Also, the direction of changes in these genes is mostly hypermethylation, although there are some genes with hypomethylation in cancers, such as SNRPN (5/22) and H19 (5/22)." (PMID 26338779, 2015).
cancer (continued). "For example, it is found that vertebrate H19 harbors both canonical and non-canonical binding sites for the let-7 family of microRNAs, which plays key roles in development and cancer." (PMID 25387074, 2014). "Analysis of 74 paired clinical GC and noncancerous tissues showed a significant upregulation (mean: 6-fold) of the expression of H19 in cancer tissues compared with matched noncancerous tissues." (PMID 24810858, 2014). "The function of the H19 gene is not known; however, recent data suggest a role in cancer progression, angiogenesis, and metastasis." (PMID 23984081, 2013). "In some cases, it seems obvious that the H19 gene activation in cancer and non-cancerous states share a common denominator in terms of the triggers and the targets." (PMID 23429271, 2013). "The H19 gene is a classical maternally expressed imprinted gene, and the aberrant methylation of the H19 DMR often occurs in genetic diseases, growth retardation, prenatal lethality, and many kinds of cancer." (PMID 22393450, 2012). "First, IGF2-P4 and H19 are reciprocally imprinted and are exclusively expressed at high levels in cancer cells and not in normal cells." (PMID 21162716, 2010). "As H19 and IGF2-P4 are expressed at very high levels in a broad spectrum of different cancers, therefore we propose a double promoter expression approach for targeted cancer therapy." (PMID 21162716, 2010). "As described for IGF2/H19, epigenetic changes at DLK1/GTL2 occur in human cancers." (PMID 15798773, 2005). "Treatment approaches that differ between estrogen-positive (ER+) and triple-negative BC cells (TNBCs) and may subsequently affect cancer biomarkers, such as H19 and telomerase, are an emanating delight in BC research." (PMID 38773429, 2024). "The combination (F2C) alleviated the proliferative malignancy of the cancer cells by downregulating enhancer of zest homolog 2 (EZH2) transcription and protein expression, resulting in decreased migration, tri-methylation of histone H3 at lysine 27 (H3K27me3) and long non-coding RNA H19 expression." (PMID 40176927, 2024). "RNA-binding protein HNRNPA2B1 is involved in the transportation and posttranscriptional regulation of numerous cancer-progression-related micro RNA (miRNAs) and long noncoding RNA (lncRNA) through binding of the specific motifs GGAG/CCCU such as miR-934, Linc01232, miR100HG, H19 and RP11." (PMID 38067326, 2023). "Exosomal lncRNA like MALAT1, growth arrest-specific 5 (GAS5), H19, HOTAIR, small ubiquitin-like modifier 1 SUMO1 pseudogene 3 (SUMO1P3) and X-inactive specific transcript (XIST) were previously shown upregulated in the blood, lung and breast tissues of cancer patients." (PMID 37153158, 2023). "Stable knockdown of exosome lncRNA H19 can significantly affect KLF4 and VEGF mRNA and protein expression levels, which affect the formation of the pre-metastatic microenvironment, inhibit cancer cell migration and invasion, and regulate the tumor microenvironment and vascular normalization." (PMID 37007117, 2023). "Indeed, a number of studies have shown a predominant activation of IGF2 fetal promoters (p2–p4) in a variety of cancers displaying IGF2 increased expression levels, with variable uncoupling of DMR0–2 methylation, along with monoallelic IGF2 and/or H19 expression." (PMID 37371750, 2023). "Additionally, it has been shown that H19 functions as a ceRNA to prevent miRNAs from degrading the essential transcriptional regulator DNA (cytosine-5)-methyltransferase 3B (DNMT3B), which is connected to the development of EMT in cancer." (PMID 36902032, 2023). "Accordingly, some cell functions of H19 have not been investigated in cancer cells." (PMID 36230902, 2022). "For instance, metformin was found to induce H19 repression and the genome-wide DNA methylation alterations by modulating the activity of H19—SAHH axis, this observation provides a novel explanation for the mechanism and function of the metformin for the epigenetic regulation effect in cancer." (PMID 36533073, 2022).
cancer (continued). "Besides, H19 and MALAT1 were upregulated in HPV+ cancers than those in HPV− cancers, which indicated that HPV might participate in the regulation of the ceRNA network." (PMID 36158885, 2022). "Additionally, upregulated genes of potential interest included H19 and IGF2 (adjusted p = 1.31e − 83, adjusted p = 5.04e − 08), both regulated by PLAGL1 and with known functions in the tumorigenesis of different cancers." (PMID 34355256, 2021). "H19 is highly expressed in exosomes derived from breast and non-small cell lung cancer (NSCLC) cells, and depletion of H19 with small interfering RNAs (siRNAs) restored doxorubicin and gefitinib sensitivity to drug-resistant cells of each of these cancer types, respectively." (PMID 33920605, 2021). "Moreover, reduced expression of H19 could induce cell apoptosis in HCC cells and other cancer cells." (PMID 32485786, 2020). "Interestingly, H19 is enriched in CAF-derived exosomes and is transported to cancer cells." (PMID 33050576, 2020). "Notably, several HALs, such as UCA1, PVT1, H19 and MALAT1, might adapt more than one action mode in different cancer types." (PMID 32370770, 2020). "Actually, H19 over-expression promoted the malignant behaviors, including aggressive proliferation, clonogenicity, EMT process, migration, invasion in vitro and rapid growth and metastasis in vivo, of different types of cancer cells while H19 silencing mitigates their malignant behaviors." (PMID 32272875, 2020). "With a fixed-effect model, shorter DFS (pooling HR = 1.50, 95 % CI = 1.22 - 1.83, p < 0.0001) and DFS/RFS/MFS/PFS (pooling HR = 1.43, 95 % CI = 1.21 - 1.69, p = 0.004) were seen in non-female cancer patients with higher H19 expression in comparison to those with lower H19 expression." (PMID 27926484, 2017). "As there are large differences in mean H19 expression among different kinds of tumors (data not shown), the HRs with 95% CI of OS and RFS from Kaplan-Meier analysis for non-female cancers of TCGA cohorts were pooled to assess the prognostic value of high H19 expression." (PMID 27926484, 2017). "Furthermore, linc-H19 was suggested to be tightly linked to tumorigenesis and to be prognostic significant for cancer progression in CRC; therefore, we compared the prognostic data of linc-H19 with that of linc-POU3F3 within these 45 cases CRC patients to assess the prognostic value of linc-POU3F3." (PMID 26510906, 2016). "However, some of these lncRNAs, including H19 and LIN00152, play a role in cancer." (PMID 26799422, 2016). "However, the pathophysiological role of H19 in this type of cancer is not clearly elucidated." (PMID 37143733, 2023). "In addition, other genes found dysregulated in our cell models (in common in A549 and SH-SY5Y cells) are H19 and PEG13, both imprinted genes whose product is a long-noncoding RNA, display differences in methylation with dysregulated patterns of imprinting in several cancers." (PMID 35163690, 2022). "Hence, we speculated that H19 might act as an oncogene in PRCC, contributing to cancer development." (PMID 34598322, 2021). "Consistent with some reports that H19 expression could serve as a poor prognostic factor, our results further indicated that high expression of H19 predicted an unfavorable prognosis in non-female cancer patients." (PMID 27926484, 2017). "However, the potential of this transcriptional targeting approach might be even greater if the cancer-specific promoters H19, IGF2-P3, and IGF2- P4, are utilized in the same therapeutic construct because many tumors that lack H19 gene expression have been found to express IGF2." (PMID 25884481, 2015).
cancer (continued). "However this targeted medicine approach could be limited, as not all cancer patients express high levels of H19." (PMID 21162716, 2010). "We identified four lncRNAs (lnc00473, H19, AC079160.1, and AC093866.1) as prognostic biomarkers, and their levels were quantified by qRT-PCR in cancer and adjacent noncancerous tissue specimens." (PMID 34987543, 2021). "Using real-time polymerase chain reaction, we analyzed five SNPs of H19 in 431 UCC patients and 431 controls without cancer." (PMID 31013794, 2019). "Interestingly, IGF-II / H19 LOI is also found in normal tissue and not just cancer, where frequently it is also not related to expression levels." (PMID 33669311, 2021). "It should be considered, however, that the inconsistency of the methylation changes of the imprinted loci outside of 11p15.5 suggests that apart from H19/IGF2 and KCNQ1OT1/CDKN1C, the other imprinted genes do not likely act as drivers of cancer progression in WT." (PMID 33217932, 2020). "Of the three GBM and GSC-specific regulated lncRNAs, PVT1 and H19 have been extensively investigated for their role in cancer development and progression, whereas FAM95B1 (ENSG00000223839.7, NONHSAG052279.2, Lnc-ANKRD20A3-51) has not been explored for its role in cancer." (PMID 39302097, 2024).
cardiovascular diseases (24 papers, 2019 to 2025). "When exposed to TNFα, a known risk factor for cardiovascular disease, H19 expression is increased, subsequently activating transforming growth factor-beta (TGF-β) signaling and promoting endothelial-to-mesenchymal transition." (PMID 40520993, 2025). "Thus, while the role of lncRNA H19 in cardiovascular diseases is well-established, the precise molecular mode of H19 function, explaining the GWAS-identified disease predispositions is still under debate." (PMID 33329688, 2020). "Because H19 is known to be involved in other cardiovascular diseases, expression levels were also assessed in ventricular tissue and the aortic arch, as well as the liver, which is known to express higher levels of H19 and was previously shown to exhibit age‐related loss of imprint." (PMID 31609547, 2019). "Previous studies have shown that H19 is closely related to many cardiovascular diseases, such as myocardial ischaemia, heart failure and atherosclerosis." (PMID 38987833, 2024). "Previous studies have shown that lncRNA-H19 (H19) is involved in many cardiovascular diseases by regulating cell proliferation and differentiation but the role of H19 in EndMT in HPH has not been defined." (PMID 38987833, 2024). "In this review, we discuss the versatile function of H19 in various types of cardiovascular diseases." (PMID 35946958, 2022). "In summary, the relationship betweenGAS5 and H19 and cardiovascular disease is relatively clear,but the relationship among MIR22HG, LINC01091, andcardiovascular disease requires further study." (PMID 39077137, 2022). "H19, a lncRNA that was among the first to be discoveredand studied, has also been reported to be involved in cardiovascular diseases,CHD, and AS." (PMID 39077137, 2022). "The aim of this manuscript is to summarize the recent findings on H19 in the cardiovascular system and to highlight the impact of its dysregulation in cardiovascular diseases." (PMID 35946958, 2022). "Previous studies have shown that expression of H19 is upregulated in cardiovascular diseases, including vascular smooth muscle cells." (PMID 35345660, 2022). "For the past few years, it has been extensively reported that lncRNA H19 and miRNA-29c both play a vital role in the development and progression of cardiovascular diseases." (PMID 35890121, 2022). "Several authors described altered H19 expression in cardiovascular diseases and related it with hypertrophic growth inhibition in cardiomyocytes and alleviation of myocardial ischemia reperfusion injury." (PMID 35453616, 2022). "Existing literature has demonstrated a high expression of H19 in patients with cardiovascular disease." (PMID 31757932, 2019). "Although some of the lncRNAs investigated in our work have been described as biomarkers in other disorders and lncRNA H19 shows evidence to be a diagnostic biomarker for cardiovascular diseases, no specific data have been reported in the setting of AAA." (PMID 40072504, 2025). "Emerging evidence demonstrates that H19 plays important roles in human cardiovascular diseases." (PMID 33664669, 2021). "Accumulating studies have indicated that lncRNA H19 might exert a crucial regulatory effect on cardiovascular disease." (PMID 31755219, 2020). "The H19/TET1 axis likely plays a crucial role in endothelial-to-mesenchymal transition and may contribute to the development of cardiovascular disease, presenting a potential therapeutic avenue for further investigation." (PMID 40520993, 2025). "In cardiovascular disease, the signal transducer and activator of transcription 3 (STAT3) pathway regulated the expression of p21 and ICAM-1 and cryptotanshinone inhibition of STAT3 prevented H19 consumption–mediated p21 induction and delayed aging." (PMID 37805704, 2023). "Besides H19 and MIAT, LINC00305 is another lncRNA with a potential role in cardiovascular diseases." (PMID 33329688, 2020).